TNF (tumor necrosis factor)
Diseases named in the same sentence as TNF in open-access papers (continued):
Sharing a sentence is not in itself a finding about the gene and the disease.
infection (continued). "Targeting TNF-α as a treatment modality has shown tremendous success, however there are several limitations associated with the current anti-TNF-α biologic drugs including: immunogenicity, life-threatening infections, resistance to treatment, complexity of manufacture and cost of treatment." (PMID 30967865, 2019). "However, in a study in BALB/cJ mice with pretreatment with antibody for TNF-α before the hRSV-infection, mice showed a significant increase of weight loss and slow recovery as compared to control mice." (PMID 30936869, 2019). "Furthermore, TNF-α-induced ICAM-1 expression associated with monocyte adhesion to HPAEpiCs was attenuated by infection with adenovirus (adv)-HO-1 or incubation with CORM-2." (PMID 30934992, 2019). "The treatment used in juvenile rheumatic patients may induce immunosuppression with consequent enhancement of infection susceptibility, mainly due to the use of steroids or tumor necrosis factor alpha (TNF-alpha) antagonists." (PMID 30810692, 2019). "However, the use of anti-TNF therapy is associated with the risk of infections because of the impairment of host immunity." (PMID 30837977, 2019). "As the risk of reactivation of latent TB and new infection is higher in patients taking anti-TNF therapy, screening by IGRA may be done once a year in case of continuous immunosuppressive therapy." (PMID 31057626, 2019). "Both the low and high accumulated dosage treatments with anti-TNF-α agents were associated with an increased risk of infection-related hospitalization (HR = 4.0, 95% CI: 2.9–5.5 in the low accumulated dosage group, HR = 3.3, 95% CI: 2.4–4.5 in the high accumulated dosage group)." (PMID 30373275, 2018). "Upon infection, adjacent innate immune cells sense pathogen-associated molecular patterns such as lipopolysaccharide and exogenous nucleotides, and secrete cytokines, including interleukin (IL) -1, IL-6, and tumor necrosis factor α (TNF-α)." (PMID 30227629, 2018). "In addition, excessive TNF, particularly in PG, was associated with peripheral infection and placental lesions." (PMID 29743113, 2018). "However, the deleterious effects of neutralising the actions of TNF, including increased susceptibility to infection, remains a major setback for this type of therapy." (PMID 29636466, 2018). "Indeed, infection experiments in the congenital neutropenic mice and in susceptible mice (TNF-α−/− C57Bl/6 mice) treated with neutrophil depletion antibodies revealed lower parasite levels in the blood circulation associated with the neutropenic state." (PMID 30046157, 2018). "A French multicenter retrospective cohort study with 41 patients with RP who were exposed to 105 biologics reported the efficacy of TCZ (n = 17) as well as TNFα inhibitors (n = 60) but a low number of complete responses and concerns about the risk of infection were reported." (PMID 30423923, 2018). "Neutralization of TNF or IFNγ during a primary Lm-gp61 infection resulted in dramatically increased susceptibility to infection in LCMV-naïve mice, indicating that neutralization of either cytokine was sufficient to reduce protection from a primary response (data not shown)." (PMID 29438281, 2018). "Anti-TNF-α agents predisposed patients with IBD to infection." (PMID 30373275, 2018). "In theory, the risk of infection and carcinogenesis might increase associated with dysfunction of specific effector cells or decreased TNF-α in AID patients receiving cell infusion." (PMID 30428931, 2018). "In addition, certain parasites also induce expression of IL-12 and tumor necrosis factor-α (TNF-α) during infection, causing tissue necrosis." (PMID 29438279, 2018). "Thus, TNF is one of the first proinflammatory cytokines produced in response to infection by pathogenic bacteria." (PMID 30467497, 2018).
infection (continued). "Anti-TNF therapies have shown their efficacy for the treatment of autoimmune inflammatory diseases, however, an increased risk of reactivation of latent tuberculosis or new infections were observed in patients." (PMID 29973541, 2018). "A low dose of 1 mg/L of both INH and RIF (INH/RIF) given from day 14 to 35 post-infection in drinking water was totally ineffective, with a drastic body weight loss, a high bacterial load by day 26, similar to untreated TNFα−/− mice." (PMID 29872095, 2018). "In addition, primates and human PBMC exposed to LCMV-WE (a virus causing hemorrhagic fever) showed that virulent infection was associated with undetectable levels of TNF-α, low levels of IL-8 in plasma and inhibition of IL-8 mRNA expression." (PMID 30373278, 2018). "Similar to TNF-α, the amount of interferon arises mainly from NK cells, but T cells also synthesize these cytokines, both cytokines are upregulated in therapeutic approaches which cause infection regression." (PMID 29854832, 2018). "Similarly, TNF-α is a pro-inflammatory cytokine and has been implicated to mediate resistance against L. donovani infection in a visceral model of infection." (PMID 29953494, 2018). "This, in turn resulted in limiting the TNF-mediated infection-associated immunopathology." (PMID 30333827, 2018). "Long-term TNF neutralization increases susceptibility to infections and skin cancer." (PMID 29295985, 2018). "Except for macrophages, TNFα deficiency negatively affects both innate and adaptive inflammatory responses, impacting mainly on B cell follicle formation and increasing murine lethality after pathogenic infection." (PMID 28910376, 2017). "However, the anti-TNFα treatment rendered the animals susceptible to the rapid relapse of the infection seen after cessation of the antibiotic treatment." (PMID 28087648, 2017). "Inflammatory processes comprise a critical response to pathogenic infection; however, the excessive production of inflammatory cytokines, such as TNF-α and IL-1β, may induce cell injury." (PMID 28821873, 2017). "Indeed, RA patients with prior exposure to TNF inhibitors were recently shown to have a greater 1-year risk of hospitalized infections compared with patients exposed to CTLA4 Ig." (PMID 28264025, 2017). "This might be true also for humans in which control of blood stage infection associated with the ratio of TNF versus IL-1076–78." (PMID 28871201, 2017). "The divergence in the frequency of the TNFα-308A allele between studies could reflect distinct mechanisms of pathogenicity and host responses resulting from infections with different Leishmania species." (PMID 28241747, 2017). "The risk of infection depends on the nature of the TNF-α blockers." (PMID 29184553, 2017). "This is why stratifying patients according to comorbidity burden and other infection risk factors can help clinicians to make more accurate risk-benefit assessments regarding anti-TNF therapy and ultimately make better-informed treatment decisions at the individual-patient level." (PMID 29246162, 2017). "Increased production of TNF-α has been associated with inflammatory conditions that might lead to pathogenesis of the local area of infection." (PMID 28525970, 2017). "We show that infection of rat intestinal epithelial cells with mature sporozoites primarily results in higher expression of genes associated with Tumor Necrosis Factor alpha (TNFα) signaling via NF-κB." (PMID 28362800, 2017). "Interestingly, the MT-TNF−/− mice succumbed to the infection similar to the complete-deficient TNF−/− mice." (PMID 28280495, 2017). "However, the anti-TNFα treatment renders the animals susceptible to relapse of the infection upon cessation of antibiotics." (PMID 28087648, 2017).
infection (continued). "Infection with α-glucan-deficient chemotype I H. capsulatum was associated with greater pulmonary levels of IFN-γ, IL-1β, IL-12, and TNFα, in association with increased weight loss, more severe pathology in lung histology, and higher pulmonary fungal burden later in the infection." (PMID 29371564, 2017). "Indeed, the only cytokine that was elevated in RAGE deficient mice upon infection with PVM was TNF-α." (PMID 28099113, 2017). "TNF−/− mice lost weight rapidly and had to be euthanized on day 25 postinfection, but the other mice did not experience body weight loss (data not shown) and were euthanized during early infection (day 28) or established infection (day 56)." (PMID 29184553, 2017). "Moreover, induction of type 1 and 2 interferon (IFN) were higher following infection with African strains associated with enhanced levels of inflammatory cytokines such as interleukin 6 (IL6) or tumor necrosis factor (TNF)." (PMID 28934211, 2017). "IFN-γ is involved in clearance of infection, whereas IL-4 and TNF-α are associated with disease." (PMID 27242782, 2016). "Consequently, the prominence of TGF-β correlates with permissibility to L. major infection, whereas high production of TNF is associated with resistance to infection." (PMID 27058234, 2016). "However, at 4 h of infection EHEC caused a sudden increase of TNF-α secretion in 0.0163 ng/ml vs. those induced by EPEC, 0.0013 ng/ml (around 10 times)." (PMID 27774437, 2016). "This study aims to evaluate whether the TNF-α/IL-10 ratio, a cytokine marker of the balance between key pro- to anti-inflammatory levels, would predict susceptibility to multiple infections." (PMID 27761434, 2016). "The present investigation compares the effect of anti-IL-17A or TNFα neutralizing antibodies side-by-side, including TNFα-deficient mice as susceptible controls, and in addition the role of IL-17F, in a commonly used M. tuberculosis H37Rv strain infection model." (PMID 27853279, 2016). "Although in TNFα-deficient mice lung infiltrating cells showed an increased granulocytic CD11b+Ly6G+ cell response, the absence of IL-17RA and/or IL-22 had little influence on CD11b+Ly6G+ cells one month post-infection." (PMID 27853279, 2016). "Therefore, a better understanding of how TNF is regulated during inflammation is needed to identify more selective ways to control disease while minimizing risk of infection." (PMID 26765224, 2016). "Indeed, infection-associated pathologies were strongly reduced in both T. brucei brucei-infected TNF−/− and TNF-R2−/− mice." (PMID 27242788, 2016). "Interestingly, co-stimulation after infection at all the times tested caused a two-fold increase in p65 phosphorylation (about 200%) that those induced by TNF-α alone." (PMID 27774437, 2016). "However, TNF-α has been linked to an initial clearance of primary infection but challenge infection elicited immune-pathology in the mouse and guinea pig model." (PMID 27219467, 2016). "Current developments in the treatments of RA include targeting cytokines or T or B lymphocyte subsets 43, 44, and the potential benefits of combining TNF inhibitors with other therapeutic agents should be carefully weighed against the increased risk of infection." (PMID 26315469, 2016). "For example, the ΔlppAB mutant-infected mice had relatively higher serum cytokines at the early infection stage, and elicited stronger T-cell proliferation which was associated with the production of TNF-α in comparison to animals infected with the ΔlppAB ΔmsbB mutant." (PMID 27891321, 2016). "We found that DOX provoked generation of TNF-α and subsequently caused the activation of NF-κB and iNOS and increased the expression of genes required to control infection and injury, such as IL-1β and IL-6, indicating severe inflammatory conditions in the brain." (PMID 27120616, 2016).
infection (continued). "In order to determine whether early TNF-α/IL-10 level is associated with the risk of a patient later developing infection to specific pathogens, we sorted the patients according to their TNF-α/IL-10 ratio z-scores." (PMID 27761434, 2016). "We therefore propose that early plasma TNF-α/IL-10 cytokine ratio may serve as a useful, risk predictor for infection hypersusceptibility in severe trauma in general." (PMID 27761434, 2016). "Although TNFα has a crucial role in protecting the host organism from pathogens, its deregulation can promote susceptibility to pathogens by impairing pathogen clearance and, ultimately, promoting maintenance of infection and death." (PMID 27351838, 2016). "However, EPEC infection caused p65 phosphorylation at 0.5 h of infection and it represented 60% of the response induced by TNF-α alone." (PMID 27774437, 2016). "Interestingly, co-stimulation with TNF-α after HB101 infection clearly induced p65 phosphorylation at 30 min of infection and caused an increase in 100%, similar to the TNF-α treatment alone." (PMID 27774437, 2016). "Furthermore, while M. marinum-infected embryos deficient in TNF signaling showed increased granuloma formation in early stages of infection, after Mabs infection of tnfr morphants the granuloma formation was almost completely abrogated." (PMID 27806130, 2016). "This antiviral mechanism may provide clues for tackling the high rise of infections caused by TNF-α inhibitor treatment in patients." (PMID 27150018, 2016). "To assess whether blocking the IL-17 cytokine family axis may affect host susceptibility to M. tuberculosis H37Rv strain infection, we investigated the effect of neutralizing IL-17A or IL-17F during acute infection, in comparison to TNFα neutralization." (PMID 27853279, 2016). "As before, immunocompromised TNFα-deficient mice served as controls for infection reactivation." (PMID 27853279, 2016). "This explains why immunosuppressive TNF therapy increases the risk of Mabs infections." (PMID 27806130, 2016). "Anti-TNF therapeutics target an important driver of the chronic inflammatory response and have had success in the clinic, but patients on this therapy are at increased risk of infection, and 80% fail to achieve long-term remission and relapse within one year." (PMID 25961845, 2015). "In the i.n. model, infection by vΔ169 caused enhanced production of several cytokines (IL-2, IL-6 and TNF-α) and chemokines (CCL11, CXCL9 and CXCL10) within 1 day p.i. and subsequent greater recruitment of macrophages and CD4+ and CD8+ T cells and increased lung weight." (PMID 26334635, 2015). "Clinical manifestations of filovirus infection, such as fever, shock, and coagulopathy, may be in part linked to induction of TNFα during infection." (PMID 26512687, 2015). "In addition, infection of pigs was associated with MΦ producing pro-inflammatory cytokines, such as IL-1α, IL-1β, IL-6, and TNF-α." (PMID 26664939, 2015). "Delayed and sustained TNF-α production has been associated with a poor prognosis during infection." (PMID 26588685, 2015). "However, in the control group, the frequency of both the variant TNF -857T and TNF -308A alleles was higher than the BM group, suggesting a possible protective role against infection." (PMID 26316174, 2015). "Nonetheless, the overall requirement of TNF for control of both mycobacterial replication and immune-mediated pathology was evident and the rapid rate of host susceptibility suggested immune deficiency during early infection." (PMID 26112704, 2015). "The combination of PCT with other markers should contribute to a more specific diagnosis and prompt treatment of patients as well as to the evaluation of the infection severity and death risk, with MR-proADM and TNF-α being recognized as markers of disease severity and death risk." (PMID 26635427, 2015). "However, TNF-α blockade caused increased susceptibility to infection, and TNF-α responses were impaired in infected CARD9−/− mice." (PMID 26336150, 2015).
infection (continued). "The overproduction of TNF may cause immunopathology, whereas defective TNF production results in uncontrolled infection." (PMID 25337995, 2014). "There may be residual confounding due to factors which have not been included in this study, which could explain the association between increased risk of infection and the combination of CS and anti-TNFα therapy." (PMID 24655394, 2014). "Physicians, therefore, should be aware that there may be an increased risk of infection, when using CS and anti-TNFα therapy together." (PMID 24655394, 2014). "In addition, we also examined the host cell response to Salmonella and LPS and verified the enhanced expression of mRNAs encoding IL-8 and TNF-α by infection with Salmonella enterica serovars Typhimurium (S. Typhimurium)." (PMID 25337908, 2014). "In addition, WT GBS stimulated greater secretion of the pro-inflammatory cytokines TNF-α and IL-6 from Siglec-E deficient macrophages both at 6 h and 24 h post infection." (PMID 24391502, 2014). "Administration of a TNF-α blocking MAb (200 μg), which inhibited both soluble and cell surface-associated forms, one day prior to infection increased the median survival time of Ifnar−/− (from 3 to 5 days, P = 0.002) and CD11c Cre+Ifnarf/f (from 3 to 8 days, P = 0.0009) mice." (PMID 24743949, 2014). "Moreover, a defective TNF-α response has been shown as a potential risk factor for infection with B. pertussis." (PMID 25333720, 2014). "TNF is an inducer of MP production in vitro, thus the associated elevated levels of MP during infection may be related to TNF overproduction." (PMID 26430675, 2014). "Thus, CS behave as immunosuppressants when associated with anti-TNFα, but are less influential when combined with DMARDs, whereas biologics seem to be associated with enhanced infection risk." (PMID 24655394, 2014). "Developing infection is a risk associated with using anti-TNF agents." (PMID 24883246, 2014). "Physicians, therefore, should be aware that there may be an increased risk of infection when using anti-TNFα and CS therapy together." (PMID 24655394, 2014). "Additionally, some studies showed that different genotypes (1 and 2) of PRRSV were able to induce different patterns of IL-10 and TNF-a, which, therefore, caused different outcomes of the infection." (PMID 24992286, 2014). "In their paper, authors report these inflammatory markers' level and speculate that high preoperative levels of serum TNF-α and IL-6 may indicate a predisposition for postoperative inflammation and infection." (PMID 27438912, 2014). "Moreover, the association CS/anti-TNFα therapy has been recently described as strong predictor of serious infections in RA." (PMID 24655394, 2014). "The important increase in the risk of infection associated with the combined treatment CS + anti-TNFα may instead be because CS, in addition to the induction of apoptosis on T lymphocytes, are able to reduce cytokine production." (PMID 24655394, 2014). "The deletion did not affect bacterial growth in BHI medium, but infection of mouse RAW 264.7 macrophages with the deletion mutant led to significantly higher TNF-α secretion in medium than that caused by the wild-type strain Symbioflor 1, revealing inhibition of stress signaling by TcpF." (PMID 25147569, 2014). "Does anti-TNF use in RA patients increase the risk of infection?" (PMID 24498926, 2013). "Protection against infection was associated with antigen-specific production of IFNγ, TNFα and IL-17 by splenocytes, however, protection against both infection and pathology required the induction of a similar pro-inflammatory response in the respiratory tract draining lymph nodes." (PMID 23613984, 2013). "In addition to histamine, calcium ionophore and phosphodiesterase inhibitors, ULVWF strings are secreted from endothelial cells that have been stimulated by cytokines (TNFα, IL-6, IL-8) associated with infection and inflammation." (PMID 23555663, 2013).